GCH1 (GTP cyclohydrolase 1)
Diseases named in the same sentence as GCH1 in open-access papers (continued):
Sharing a sentence is not in itself a finding about the gene and the disease.
atherosclerosis (9 papers, 2011 to 2023). A disease characterized by the build-up of fatty material and calcium deposition in the arterial wall resulting in partial or complete occlusion of the arterial lumen. "Bone marrow chimeras revealed that loss of Gch1 in both endothelial cells and leucocytes is required to accelerate atherosclerosis." (PMID 29596571, 2018). "Loss of Gch1 from either endothelial cells or leucocytes alone did not alter atherosclerotic plaque burden in either male or female mice, indicating that deficiency of Gch1 from both endothelial cells and leucocytes is required to increase atherosclerosis burden." (PMID 29596571, 2018). "Transgenic animal models support that Gch1 deficiency and reduced vascular BH4 accelerate atherosclerosis whereas supplementation of BH4 or Gch1 expression reverse these deficits and retard atherosclerosis." (PMID 30847343, 2019). "We found that loss of Gch1 from either cell type alone was insufficient to accelerate atherosclerosis, indicating that Gch1 from both endothelial cells and leucocytes was required for accelerated plaque formation." (PMID 29596571, 2018). "We next aimed to assess how Gch1 deletion and BH4 deficiency in endothelial cells and leucocytes altered the development of atherosclerosis." (PMID 29596571, 2018). "This study confirmed the pathological role of uncoupled eNOS in atherosclerosis, since treatment with BH4 or crossing with mice with endothelial cell targeted Gch1 overexpression re-coupled eNOS, resulting in a reduction in atherosclerosis." (PMID 29596571, 2018). "The generation of a new mouse model for targeted Gch1 deletion in atherosclerosis enables important new questions to be addressed on the requirement for BH4." (PMID 29596571, 2018). "In order to evaluate the contribution of specific cell types in the progression of atherosclerosis, we generated bone marrow chimeras in which Gch1 was selectively deleted in either endothelial or leucocytes." (PMID 29596571, 2018). "Likewise, restoring the miR-92a/NOX and miR-133/GCH1 regulatory axes could ameliorate oxidative injury in atherosclerosis." (PMID 32664383, 2020). "Over-expression of GCH1 restores ischemic preconditioning during hyperglycemia, protects against acute cardiac allograft rejection, attenuates blood pressure progression in salt-sensitive low-renin hypertension, and reduces endothelial dysfunction and atherosclerosis in ApoE-knockout mice." (PMID 22479495, 2012). "We have generated a novel mouse model of endothelial cell and leucocyte-targeted Gch1 deletion, crossed with the hyperlipidemic ApoE–/– mouse, to test the cellular requirement for BH4 in the pathology of atherosclerosis." (PMID 29596571, 2018). "The objective of this study is to characterize the role of GTP cyclohydrolase 1 (GTPCH1), the rate‐limiting enzyme for de novo tetrahydrobiopterin (BH4) synthesis, in the smoking‐accelerated atherosclerosis and the mechanism involved." (PMID 30091833, 2018). "These novel findings reveal contrasting endothelial cell and leucocyte requirements for Gch1 and BH4 in the progression of atherosclerosis and identify new BH4-dependent determinants of inflammatory cell redox signalling and foam cell formation." (PMID 29596571, 2018). "In conclusion, we have shown for the first time a key role for endothelial cell and leucocyte Gch1 and BH4 in the progression of atherosclerosis." (PMID 29596571, 2018). "They found that the overexpression of GTP cyclohydrolase 1 (GTPCH1), the rate-limiting enzyme in tetrahydrobiopterin (BH4) de novo synthesis, and the BH4 supplement were protective against nicotine-accelerated atherosclerosis." (PMID 32331221, 2020). "Given the changes observed in both endothelial cell and macrophage biology in the absence of Gch1 we next sought to determine the contributions of these cell types to the observed increase in atherosclerosis in Gch1fl/flTie2CreApoE–/– mice." (PMID 29596571, 2018).
hepatocellular carcinoma (8 papers, 2021 to 2026). A malignant tumor that arises from hepatocytes. "In contrast, the silencing of GCH1 promotes hepatocellular carcinoma growth by inhibiting ASK1/p38 signaling 30, and its role in cervical cancer remains to be elucidated." (PMID 41583517, 2026). "There are reports of GCH1 exhibiting high expression in some tumors, such as hepatocellular carcinoma, esophageal squamous cell carcinoma, and gastric cancer, and its association with tumor progression, metastasis, and poor prognosis." (PMID 38903179, 2024). "To validate FSP1 as a central target of ginsenoside RK1-mediated ferroptosis in hepatocellular carcinoma, we engineered overexpression plasmids for GCH1, DHODH, GPX4, and FSP1, respectively, and transfected them into HepG2 cells." (PMID 39065721, 2024). "In hepatocellular carcinoma, GCH1 silencing promotes cell growth by activating superoxide anion-mediated ASK1/p38 signaling." (PMID 36999051, 2023). "In a recent study, GCH1 was found enriched in human hepatocellular carcinoma." (PMID 33477898, 2021). "GCH1-L and STK39-L, two longer splice variants of GCH1 and STK39, promote the tumorigenic potential of hepatoma cells, whereas their shorter splice variants have no apparent effects." (PMID 39850359, 2025). "Remarkably, while overexpression of GCH1, DHODH, and GPX4 failed to significantly increase cell viability in hepatocellular carcinoma cells, overexpression of FSP1 led to a substantial increase in cell viability." (PMID 39065721, 2024). "Notably, overexpression of GCH1, DHODH, and GPX4 did not mitigate the heightened ferroptosis sensitivity induced by ginsenoside RK1 in hepatocellular carcinoma cells." (PMID 39065721, 2024).
glioma (7 papers, 2019 to 2026). A benign or malignant brain and spinal cord tumor that arises from glial cells (astrocytes, oligodendrocytes, ependymal cells). "Additionally, the expression of GCH1 and FSP1 increased with increasing malignancy of the tumor; GPX4, FSP1, and GCH1 were highly expressed in patients with glioma and wild-type IDH1 compared to mutant IDH1." (PMID 35174170, 2021). "However, GCH1 was detected in glioma samples, and increased with tumor grades." (PMID 31500569, 2019). "Conversely, circLRFN5 overexpression reduces glioma CSC viability, proliferation, and tumorigenicity by inducing PRRX2/GCH1 - mediated ferroptosis." (PMID 41601687, 2026). "Survival analysis also demonstrated that, similar to our published findings with GCH1, elevated expression of SPR or DHFR correlated with worse survival of glioma patients." (PMID 31500569, 2019). "CircLRFN5 can mediate paired related homeobox 2 (PRRX2) via the ubiquitin proteasome pathway, and in gliomas, PRRX2 activates transcriptional upregulation of GTP cyclohydrolase 1 (GCH1) expression, a substance that inhibits ferroptosis by producing the antioxidant tetrahydrobiopterin (BH4)." (PMID 37152286, 2023). "Using HPAanalyze, we confirmed our published finding that GCH1 was elevated in glioma in comparison to non-tumor brain tissue." (PMID 31500569, 2019). "GPX4, FSP1, and GCH1 were highly expressed, while DHODH expression was low in patients with gliomas with a 1p19q non-codeletion compared to those with a 1p19q codeletion." (PMID 35174170, 2021). "Our analysis showed that GPX4, FSP1, GCH1, and DHODH were more highly expressed in tumor tissue than in non-tumor brain tissue, especially in high-grade, IDH1 wild type, 1p19q non-codeletion gliomas, suggesting that glioma cells had a strong potential to resist ferroptosis." (PMID 35174170, 2021).
phenylketonuria (6 papers, 2012 to 2025). Phenylketonuria (PKU) is the most common inborn error of amino acid metabolism and is characterized by mild to severe mental disability in untreated patients. "To develop a rapid method for the diagnosis of phenylketonuria (PKU) and tetrahydrobiopterin (BH4) deficiency, we designed a multiplex, PCR-based primer panel to amplify all the exons and flanking regions (50 bp average) of six PKU-associated genes (PAH, PTS, GCH1, QDPR, PCBD1 and GFRP)." (PMID 24705691, 2014). "Mutation of GCH1 resulted in greatly reduced BH4 levels which has been shown to cause neurological diseases such as dopamine-responsive dystonia (DRD) and atypical severe phenylketonuria (PKU)." (PMID 22479495, 2012).
Ataxia (5 papers, 2009 to 2025). Ataxia refers to impaired coordination of voluntary muscle movement. "Two of these individuals were found to harbour pathogenic/likely pathogenic variants in GCH1 and PRRT2, respectively, although these findings were of uncertain clinical relevance to the cerebellar ataxia phenotype." (PMID 40007153, 2025).
depression (4 papers, 2012 to 2025). "The 15 target genes include DYNLT1, GCH1, TOR1B, DISC1, MEF2A and ST3GAL5 that to date were never related to an IFN-α regulation while all of them have been described in association with brain development or depression." (PMID 22701688, 2012).
gastric cancer (4 papers, 2023 to 2026). A primary or metastatic malignant neoplasm involving the stomach. "High PBX1 expression promotes GTP cyclohydrolase 1 (GCH1) transcription and the malignant progression of gastric cancer." (PMID 39090090, 2024).
colorectal cancer (3 papers, 2022 to 2023). A primary or metastatic malignant neoplasm that affects the colon or rectum. "GCH1 has been reported to be associated with ferroptosis in esophageal and colorectal cancers." (PMID 36902448, 2023).
developmental delay (3 papers, 2022 to 2025). "Functional annotation and Human Phenotype Ontology (HPO) implication of PTS and GCH1 related to HPP comprise heel bone mineral density (rs3819331, rs17127816), intellectual disability, global developmental delay, seizure, hypotonia, recurrent fever, scoliosis, and talipes equinovarus." (PMID 41158885, 2025).
esophageal cancer (3 papers, 2020 to 2024). A primary or metastatic malignant neoplasm involving the esophagus. "As GCH1 depletion is reportedly involved in ferroptosis, we investigated the function of GCH1 in relation to ferroptosis in esophageal cancer." (PMID 39723384, 2024). "The hnRNP D, that is overexpression in Eca-109 esophageal cancer cell line, has been recognized to bind the 3′-UTR AU-rich motifs of GTP cyclohydrolase (GCH1) transcripts causing GCH1 overexpression and enhanced cell proliferation and colony formation." (PMID 32596243, 2020). "Although studies have reported on the association between lipid peroxidation markers and the prognosis in esophageal cancer, the association with the accumulation of lipid peroxidation markers and GCH1 has not been investigated." (PMID 39723384, 2024). "Such nonenzymatic functions of GCH1 may contribute to its favorable prognosis in esophageal cancer." (PMID 39723384, 2024).
Hyperglycemia (3 papers, 2015 to 2018). An increased concentration of glucose in the blood. "Transfection of miR-133a inhibitor significantly decreased intracellular miR-133a level, and similar to what we found in the ischemic muscle, miR-133a antagonism in HUVECs under hyperglycemia and HSS conditions increased GCH1 protein expression, tube formation, NO and cGMP, and decreased ROS level." (PMID 29789398, 2018).
lung carcinoma (3 papers, 2014 to 2025). "Pharmacological inhibition of GCH1 sensitizes lung cancer cells to ferroptosis inducers, suggesting a potential therapeutic approach." (PMID 40619484, 2025). "Although the exact mechanisms remain unknown, evidence suggests that erastin induction downregulates the translocation of nuclear factor erythroid 2-related factor 2 (NRF2) within the nucleus in lung cancer and GCH1 is one of the downstream genes of NRF2 in skin cells." (PMID 35223839, 2022).
malaria (3 papers, 2014 to 2018). Malaria is a serious and sometimes fatal disease caused by a parasite that commonly infects a certain type of mosquito which feeds on humans. "Copy number polymorphism of P. falciparum gch1 is found in malaria parasites from certain endemic countries, with some isolates from Thailand containing more than ten copies of gch1." (PMID 24745605, 2014). "GCH1 mRNA transcription was at least as high in each malaria group [UM (1.35 [IQR 1.11–1.97] 2-ddCt) and CM (1.39 [IQR 0.88–1.77] 2-ddCt)] relative to controls (0.82 [IQR 0.60–0.84] 2-ddCt) (p = 0.082)." (PMID 25764173, 2015). "With a series of the new findings on the significance of P. falciparum GCH1, it is important to characterize this enzyme from malaria parasites." (PMID 24745605, 2014). "A joint analysis of gch1 CNVs, pfdhfr and pfdhps SNPs may therefore shed more light on the molecular mechanisms of SP resistance and how these resistant isolates are maintained in circulation in malaria endemic areas like Ghana." (PMID 30265714, 2018). "The inhibition of P. falciparum GCH1 might be able to prevent drug resistance evolution of other drug-targeted folate enzymes and could become a new strategy for fighting the emerging threat of malaria drug resistance." (PMID 24745605, 2014). "We conclude that PBMC GCH1 mRNA and pterin synthesis is not decreased in children with malaria and does not account for the lower BH4." (PMID 25764173, 2015). "The finding indicates that feverish temperature in symptomatic malaria patients would not interfere with the activity of P. falciparum GCH1." (PMID 24745605, 2014).
melanoma (3 papers, 2021 to 2022). A malignant, usually aggressive tumor composed of atypical, neoplastic melanocytes. "Regarding WM983B metastatic melanoma cells, an increased GCH1/GTPCH1 expression is associated with a high BH4 concentration." (PMID 35682659, 2022). "Since we have previously suggested that eNOS uncoupling is associated with melanoma cell growth and apoptosis resistance, we expected to observe decreased Gch1 expression and activity." (PMID 34502464, 2021). "GCH1 expression was higher in WM983B metastatic melanoma cells in relation to less aggressive melanoma cells WM1152C and WM793." (PMID 35682659, 2022). "Surprisingly, we found increased expression of Gch1 mRNA in 4C11− and 4C11+ melanoma cells when compared with melan-a melanocytes and 4C pre-malignant melanoma cells." (PMID 34502464, 2021). "The beneficial effect of GCH1 expression on melanoma patient survival may be related to the immune response." (PMID 34447410, 2021). "Moreover, public data from Oncomine and TCGA showed that high GCH1 expression correlates with melanoma aggressiveness, increased expression of PTS and SPR, and decreased GCHFR expression in melanoma when compared to benign nevi." (PMID 34502464, 2021). "Accordingly, here, we observed that the GCH1 gene levels and GTPCH1 protein expression are higher in WM1552C RGP and WM983B metastatic melanoma cell lines when compared to melanocytes." (PMID 35682659, 2022). "Recently, through a murine melanoma model, we showed that there is an increase in the levels of Gch1 and other genes involved in the de novo BH4 biosynthesis pathway during melanoma progression." (PMID 35682659, 2022). "Initially, the expression of GCH1 was analyzed by real-time qPCR and was found to be increased in WM1552C and WM983B melanoma cells compared to melanocytes." (PMID 35682659, 2022). "Therefore, these circumstances could explain the Gch1 upregulation observed in melanoma cells." (PMID 34502464, 2021). "Data sets from TCGA showed increased GCH1 expression along with melanoma progression (n = 248) and decreased expression of GCHFR in melanoma (n = 461) compared with normal skin (n = 558)." (PMID 34502464, 2021).
Obesity (3 papers, 2012 to 2023). Accumulation of substantial excess body fat. "On the immune side, obesity may cause M2 macrophages ferroptosis due to damage to iron-rich ATMs (MFehi) and antioxidant ATMs (Mox), and lead to Treg cells ferroptosis through reductions in NRF2, GPX4, and GCH1 levels." (PMID 36479119, 2022). "Currently, the GCH1-based ferroptosis inhibition pathway only focuses on the therapeutic feasibility of tumors and cancer cells, with no obesity-related studies as of yet." (PMID 36479119, 2022).
triple-negative breast carcinoma (3 papers, 2022 to 2026). An invasive breast carcinoma which is negative for expression of estrogen receptor (ER), progesterone receptor (PR), and human epidermal growth factor receptor 2 (HER2). "Although the expression pattern of GCH1 in cancer tissues has not been well-documented, GCH1 is reportedly upregulated in breast and ovarian cancers, and that high GCH1 expression is reportedly associated with a shorter OS in triple-negative breast cancer." (PMID 39723384, 2024).
abdominal aortic aneurysm (2 papers, 2018 to 2023). Enlargement and ballooning of the vessel that supplies arterial blood to the abdomen, pelvis and legs. "EC-specific deletion of GTP-cyclohydrolase I (GCH1), an enzyme that prevents eNOS uncoupling, renders mice more susceptible to abdominal aortic aneurysm (AAA) upon angiotensin II challenge." (PMID 37909406, 2023).
autism (2 papers, 2019 to 2025). Persistent deficits in social interaction and communication and interaction as well as a markedly restricted repertoire of activity and interest as well as repetitive patterns of behavior. "GCH1 expression increases in response to valproic acid, an anti-epileptic drug associated with behavioral deficits in mice and increased risk of autism in humans after in utero exposure." (PMID 31673306, 2019).
Autoimmunity (2 papers, 2022 to 2024). The occurrence of an immune reaction against the organism's own cells or tissues. "A recent study revealed that GCH1 had a remarkably positive impact on T-cell proliferation and immune response in autoimmunity and cancer." (PMID 36072600, 2022). "Specifically, inhibition of BH4 synthesis in vivo reportedly abolishes T cell-mediated autoimmunity and allergic inflammation, whereas GCH1 overexpression increases BH4 levels, leading to increased responses by CD4- and CD8-expressing T cells and enhanced antitumor activity in vivo." (PMID 39723384, 2024).
breast invasive carcinoma (2 papers, 2022 to 2023). "Thus, we first evaluated the expression level of GCH1 and found that GCH1 was significantly elevated in breast invasive carcinoma and ovarian cancer." (PMID 36793373, 2023).